CNR2 (cannabinoid receptor 2)
Diseases named in the same sentence as CNR2 in open-access papers (continued):
Sharing a sentence is not in itself a finding about the gene and the disease.
tumor (continued). "In our study, we decided to focus only on cannabinoid receptor 2 agonists since only a small number of preclinical studies have evaluated the impact of CB2 agonists and their effects following long-term treatment on tumor growth and cancer cell proliferation." (PMID 35242036, 2022). "Interestingly, it was shown that the cannabinoid receptor 2 (CB2) was overexpressed in patients with non-small cell lung cancer (NSCLC) and tumor growth and lung metastasis was remarkably inhibited by CB2 agonists." (PMID 33446187, 2021). "Among them, the expression of CNR2, GIP, GNGT1, NPY1R, SSTR5, and LEP in tumor tissue was significantly lower than in normal tissue, while the expression of GPSM2, and NMU was significantly highly expressed in tumor tissue." (PMID 33169793, 2020). "Two targets, IL-4Rα and cannabinoid receptor 2 (CB2), were validated and confirmed to regulate both IL-6 and IL-10 production in TAMs, contributing to autocrine/paracrine activation of STAT-3 in macrophages and tumour cells." (PMID 28381274, 2017). "To investigate the role of cannabinoid receptor 2 (CB2) in skin carcinogenesis, we used the multi-stage chemical carcinogenesis model, wherein a tumor initiator (7,12- dimethylbenz[a]anthracene, DMBA) is applied topically, followed by a tumor promoter (12-O-tetradecanoylphorbol-13-acetate, TPA)." (PMID 37175480, 2023). "The expression levels of CNR1, CNR2 and FAAH did not correlate to the tumor cell content in the tissue as measured by flow cytometry." (PMID 25594062, 2014).
cancer (103 papers, 2006 to 2026). A tumor composed of atypical neoplastic, often pleomorphic cells that invade other tissues. "The cannabinoid receptor CNR2 (encoded by a gene in the commonly deleted 1p36 region) is a relatively unexplored target in cancer." (PMID 31900415, 2020). "Emerging evidence has demonstrated that cannabinoid receptor 2 (CB2) is involved in a number of diseases, such as neurodegenerative disorders and various types of cancer, making it an attractive pharmacological target." (PMID 39974643, 2025). "Targeting the endocannabinoid system, and in particular cannabinoid receptor 2 (CB2), has been repeatedly proposed as a promising option against a vast array of cancer types, ranging from hematological to solid tumors." (PMID 37175480, 2023). "Our results showed that cancer-specific survival was increased by postoperative analgesia with morphine, cannabinoid receptor 2, and opioid growth factor receptor cancer tissue gene expressions but was reduced by delta opioid receptor gene expressions." (PMID 37627066, 2023). "Since cannabinoid receptors have been the subject of intensive cancer research, in particular, cannabinoid receptor 2 (CB2) holds greater attention due to its expression in cells of the immune system where CIK cells also play an important role." (PMID 35409142, 2022). "By reviewing previous studies, we found that there were fewer reports between SLC6A2 and tumors, but we found that CNR2 plays a role in multiple cancers." (PMID 33754011, 2021). "Some of the novel pharmacological therapies that have been tried in cancer pain management include cannabinoid receptor 2 (CB2) agonist (for neuropathic pain); tetrodotoxin; botulism toxin (post-mastectomy pain] and soy isoflavones." (PMID 34336485, 2021). "Since CNR2 is mainly expressed in immune cells, specific blockade of the CNR2 signaling may avoid the neurological side effects, and thus offer a promising option for the treatment of cancer and other immune-related diseases." (PMID 35383142, 2022). "We therefore examined the mRNA expression of seven cannabimimetic receptors – CNR1 (CB1), CNR2 (CB2), GPR55, TRPV1, TRPV2, TRPA1, TRPM8 – and found them to be differentially expressed amongst the 12 tested cancer cell lines." (PMID 31289609, 2019). "CNR2 specific agonists (JWH-015 and JWH-133) inhibit growth through different mechanism including inhibition of CXCL12/CXCR4 axis, cyclo-oxygenase-2 (COX-2) expression and induction of apoptosis in different cancer types." (PMID 27213582, 2017).
neurodegenerative disease (19 papers, 2005 to 2025). A disorder of the central nervous system characterized by gradual and progressive loss of neural tissue and neurologic function. "1,5-Disubstituted tetrazoles are valuable side chains in cannabinoid receptor 2 (CB2) agonists used to treat chronic pain and neurodegenerative diseases." (PMID 39795100, 2024).
infection (10 papers, 2017 to 2025). The state of being infected such as from the introduction of a foreign agent such as serum, vaccine, antigenic substance or organism. "Our results demonstrated an upregulation of CNR2 when HIV is activated and decreased the infection with cannabinoid treatments." (PMID 37147420, 2023).
kidney disease (5 papers, 2016 to 2024). "Recent studies have suggested that targeting the endocannabinoid system, particularly the cannabinoid receptor 1 (CB1) and cannabinoid receptor 2 (CB2), may have therapeutic potential in various kidney diseases." (PMID 38360685, 2024).
peripheral neuropathy (4 papers, 2012 to 2023). A disorder affecting the peripheral nervous system. "Links between cannabinoid receptor 2 (CB2R) and peripheral neuropathy have been established in animal models using nerve transection, chemotherapy-induced pain, and various other stimuli." (PMID 31354896, 2019).
neurological disorders (3 papers, 2017 to 2024). "Rare genetic variants in the core endocannabinoid system genes CNR1, CNR2, DAGLA, MGLL and FAAH were identified in molecular testing data from 6,032 patients with a broad spectrum of neurological disorders." (PMID 29145497, 2017).
psychiatric disorder (3 papers, 2018 to 2025). A disorder characterized by behavioral and/or psychological abnormalities, often accompanied by physical symptoms. "The polymorphisms in the CB2R gene (CNR2) are frequent, and are commonly observed in human population associated with psychiatric disorders." (PMID 30042304, 2018). "In addition, our studies on the association of human CNR2 gene polymorphisms suggested that these polymorphisms are a common factor in some psychiatric disorders." (PMID 30042304, 2018).
CNR2 also shares sentences with these, for which no sentence is quoted: glioblastoma (18 papers); hepatocellular carcinoma (12); osteoarthritis (10); amyotrophic lateral sclerosis (8); inflammatory bowel disease (8); ischemia (7); systemic sclerosis (7); dermatitis (6); diabetic nephropathy (6); endometrial carcinoma (6); epilepsy (6); inflammation (6); memory impairment (6); metabolic disease (6); alcoholic liver diseases (5); asthma (5); bone cancer (5); cervical carcinoma (5); immune disorders (5); autism (4); B-cell lymphoma (4); cardiovascular disease (4); HIV-1 infection (4); leukemia (4); lymphoma (4); mood disorder (4); psoriasis (4); viral infection (4); acute lymphoblastic leukemia (3); acute myeloid leukemia (3).
A further 214 diseases each share a sentence with CNR2 in 3 papers or fewer.